PODXL (podocalyxin like)
Diseases named in the same sentence as PODXL in open-access papers (continued):
Sharing a sentence is not in itself a finding about the gene and the disease.
glioma (6 papers, 2013 to 2025). A benign or malignant brain and spinal cord tumor that arises from glial cells (astrocytes, oligodendrocytes, ependymal cells). "Higher grade tumors had higher levels of immunoreactivity and there was a statistically significant association between PODXL expression and glioma grade (p<0.0001)." (PMID 24146797, 2013). "Moreover, the results presented that high PODXL expression was distinctly associated with worse OS in patients with glioma (HR=1.92, 95%CI=1.48-2.49, p<0.00001)." (PMID 28881743, 2017). "Taken together, these findings demonstrate that PODXL is expressed in primary human GBMs and that its expression level correlates positively with glioma grade." (PMID 24146797, 2013). "To further investigate the expression of PODXL in human gliomas, we examined the relationship between PODXL expression and tumor grade by performing immunohistochemistry on TMAs containing a total of 148 gliomas." (PMID 24146797, 2013). "During review of this manuscript, an additional study investigating the role of PODXL in glioma cell invasion was published, demonstrating that expression of PODXL increases in vitro invasion and protects against chemotherapeutic activity." (PMID 24146797, 2013). "Our findings demonstrate that PODXL is involved in GBM stem-like cell proliferation and oncosphere formation and that high PODXL expression correlates with glioma grade and decreased overall survival in patients with GBMs." (PMID 24146797, 2013). "Our analysis, utilizing the REMBRANDT data set, demonstrated that up-regulation of PODXL predicts worse survival for patients with glioma." (PMID 24146797, 2013). "Patients with gliomas and up-regulated PODXL expression had a significantly shorter overall survival than those with intermediate PODXL expression (p<0.0001)." (PMID 24146797, 2013). "We additionally examined the expression of PODXL in gliomas and demonstrated that PODXL is overexpressed in the majority of GBMs and that PODXL expression is correlated with tumor grade, demonstrated in both fixed specimens and fresh tissue." (PMID 24146797, 2013). "In this study, we functionally characterize this protein in GBM stem-like cells and investigate the clinical significance of expression of PODXL in gliomas." (PMID 24146797, 2013). "PODXL expression was up-regulated in 85 gliomas and expressed at an intermediate level in 257 gliomas." (PMID 24146797, 2013). "Taken together, these studies demonstrate that PODXL expression is correlated with glioma grade and that PODXL is a marker for overall worse survival in patients with GBMs." (PMID 24146797, 2013). "Additional studies will be necessary to further explore the role of PODXL in glioma invasion." (PMID 24146797, 2013). "Moreover, high PODXL expression correlates with increasing glioma grade and decreased overall survival in patients with GBM." (PMID 24146797, 2013). "Finally, PODXL expression directly correlated with increasing glioma grade and was a marker for poor outcome in patients with GBM." (PMID 24146797, 2013). "Finally, high PODXL expression correlates with glioma grade and poorer outcome in patients with GBM." (PMID 24146797, 2013). "In addition, four studies focused on the prognostic role of PODXL in CRC, one study focused on the glioma, one focused on the UBC, one paid attention to the BC, three focused on the PC, and two studies focused on the prognostic role of PODXL in EGAC." (PMID 28881743, 2017).
lung adenocarcinoma (6 papers, 2017 to 2021). A carcinoma that arises from the lung and is characterized by the presence of malignant glandular epithelial cells. "In lung adenocarcinoma cell line A549, PODXL is upregulated following TGFβ treatment in association with effective EMT transformation." (PMID 34201212, 2021). "Additionally, it was found that the altered expression of PODXL lead to the molecular changes (e.g., vimentin, E-cadherin, collagen I) associated with TGF-β induced EMT of human lung adenocarcinoma cells, demonstrating the significant role of PODXL in the EMT and metastasis of cancers." (PMID 29748877, 2019). "Cell motility and migration are also increased in PODXL-overexpressed cells, as observed in aggressive lung adenocarcinomas." (PMID 34201212, 2021). "Moreover, silencing of PODXL level in human lung adenocarcinoma cells decreased the spreading and migration abilities and resulted in the phenotype changes of cells by affecting EMT-associated protein, such as vimentin and E-cadherin." (PMID 29748877, 2019). "Moreover, in lung adenocarcinoma, PODXL overexpression induced epithelial-to-mesenchymal transition (EMT)." (PMID 31083655, 2019). "In A549 lung adenocarcinoma cell line, PODXL expression increased during transforming growth factor-beta (TGF-beta)-induced EMT, and PODXL silencing reduced morphological changes and molecular markers associated with EMT." (PMID 32046309, 2020).
lymph node metastases (6 papers, 2013 to 2019). "The high level of PODXL was detected in GC tissues with advanced T stage, lymph node metastasis, Union for International Cancer Control stage and poor differentiation." (PMID 29748877, 2019). "Similar results were obtained when the survival analyses were stratified by primary tumor location, and when considering PODXL expression in primary tumors and lymph node metastases separately." (PMID 27478410, 2016). "Considering the median value of PODXL expression in the lymph nodes for each patient, the concordance of PODXL expression between primary CRCs and lymph node metastases was 93,5% and the correlation was statistically significant (p<0.001)." (PMID 23819542, 2013). "PODXL expression could be assessed in pre-neoadjuvant biopsies from 99/148 (67%) patients, in post-neoadjuvant resected primary tumors from 102/118 (86%) patients, and in post-neoadjuvant resected lymph node metastases from 47/66 (71%) patients." (PMID 30355278, 2018). "PODXL expression could be assessed in in 63/65 (96.9 %) primary I-type carcinomas and 24/30 (80.0 %) lymph node metastases, and in 107/108 (99.1 %) primary PB-type carcinomas and 63/75 (84.0 %) corresponding lymph node metastases." (PMID 26028992, 2015). "PODXL expression could be evaluated in 31/32 (96,9%) patients with lymph node metastases." (PMID 23819542, 2013). "In the present study, although negative conversion of membranous PODXL expression from primary tumour to lymph node metastasis was far more common than positive conversion, a few cases displayed the latter phenomenon." (PMID 26028992, 2015). "In this study, we compared PODXL expression in primary CRC and synchronous lymph node metastases." (PMID 23819542, 2013). "Additionally, the level of PODXL in GC tissues with lymph node metastasis was obviously higher in comparison with one without lymph node metastasis and the statistical difference was significant." (PMID 29748877, 2019).
osteosarcoma (6 papers, 2017 to 2024). A usually aggressive malignant bone-forming mesenchymal neoplasm, predominantly affecting adolescents and young adults. "PODXL has been shown to significantly mediate cisplatin resistance in oral tongue squamous carcinoma and osteosarcoma cells." (PMID 38553472, 2024). "Furthermore, enforced expression and PODXL silencing studies in MG-63 and U2OS osteosarcoma cell lines showed that PODXL induces cisplatin chemoresistance via PI3K/AKT signaling pathway." (PMID 32046309, 2020).
Parkinsonism (6 papers, 2017 to 2024). Characteristic neurologic anomaly resulting from degeneration of dopamine-generating cells in the substantia nigra, a region of the midbrain, characterized clinically by shaking, rigidity, slowness of movement and difficulty with walking and gait. "Except for PODXL, mutations in genes causing juvenile Parkinsonisms are always related to complex phenotypes in which pallido-pyramidal signs, oculomotor abnormalities, cognitive impairment, and seizures variably occur." (PMID 34630269, 2021). "Recently, a homozygous frameshift mutation in the PODXL gene was described as a causal factor for juvenile parkinsonism." (PMID 29163333, 2017). "Furthermore, whole-exome sequencing did not identify pathogenic (or likely pathogenic) variants in the PINK1, SYNJ1, and PODXL genes and other known genes associated with early-onset parkinsonism." (PMID 39332416, 2024). "Using this assay, we document lumenal size defects in NPC carrying loss-of-function mutations of PODXL, a feature that may have implications for early onset Parkinson’s disease caused by loss of PODXL activity." (PMID 33178701, 2020). "Though the exact mechanism underlying the link between reduced or impaired PODXL activity and Juvenile Parkinsonism remains to be elucidated, we speculate that lumenal expansion during early neural tube morphogenesis may be impaired and that this in turn could perturb the forming neural epithelium." (PMID 33178701, 2020).
acute myeloid leukemia (5 papers, 2017 to 2024). Acute myeloid leukemia (AML) is a group of neoplasms arising from precursor cells committed to the myeloid cell-line differentiation. "In another report, the analysis of molecular and clinical data of 166 patients with acute myeloid leukemia from The Cancer Genome Atlas revealed a correlation between low expression of PODXL-targeting miR-199b and poor survival outcome." (PMID 32046309, 2020). "Moreover, the cases of acute myeloid leukemia expressing higher levels of PODXL also displayed increased blast cell counts and higher levels of markers associated with unfavorable prognosis." (PMID 32046309, 2020). "Additionally, the expression of the PODXL transcriptional regulator Wilms’ tumor I is observed in many blast cells of ALL and acute myelocytic leukemia." (PMID 38879474, 2024).
bladder cancer (5 papers, 2015 to 2021). "Up-regulated miR-1301 inhibits PODXL, activates the Wnt/β-catenin signaling pathway, and promotes the growth of bladder cancer cells." (PMID 35070996, 2021). "A study found that in bladder cancer, NNT-AS1 can up-regulate podocalyxin-like (PODXL) by sponging miR-1301-3p, which in turn activates the Wnt pathway-related proteins, including CDK1, cyclin D1, MYC, AXIN2, and CTNNB1 (β-catenin)." (PMID 33113895, 2020).
oral squamous cell carcinoma (5 papers, 2017 to 2022). "In oral squamous cell carcinoma cell lines, hypomethylation of PODXL promoter has been associated with aggressiveness." (PMID 32046309, 2020). "In SAS human oral squamous cell carcinoma cell line, silencing of PODXL abrogated cell proliferation and colony formation." (PMID 32046309, 2020). "A core fucose-deficient monoclonal antibody (mAb) of PODXL might be a new antibody-based therapy method against PODXL high-expressed oral squamous cell carcinoma." (PMID 32615943, 2020).
periampullary adenocarcinoma (5 papers, 2015 to 2021). An adenocarcinoma that arises from the periampullary region. "In particular, the membranous expression of PODXL has been reported to be a biomarker for improved treatment stratification of patients with periampullary adenocarcinoma." (PMID 34440856, 2021). "Membranous expression of PODXL is significantly higher in PB-type than in I-type periampullary adenocarcinomas and an independent factor of poor prognosis in the latter." (PMID 26028992, 2015). "Membranous expression of PODXL is significantly higher in pancreatobiliary type as compared with intestinal type periampullary adenocarcinomas and an independent factor of poor prognosis in the latter." (PMID 26028992, 2015). "Immunohistochemical expression of PODXL was analysed in tissue microarrays with primary tumours and a subset of paired lymph node metastases from 175 patients operated with pancreaticoduodenectomy for periampullary adenocarcinoma." (PMID 26028992, 2015). "The aim of the present study was therefore to examine the clinicopathological correlates, prognostic and predictive significance of tumour-specific PODXL expression in a retrospective cohort of pancreatic and periampullary adenocarcinoma, with particular reference to morphological subtypes thereof." (PMID 26028992, 2015). "Therefore, the results from the present study indicate that PODXL could be used as a predictive marker for adjuvant treatment of periampullary cancer with intestinal morphology, and possibly also ampullary PB-type tumours." (PMID 26028992, 2015). "In this translational study we investigated PODXL and EGFR and demonstrated a significant relationship between the overexpression of these proteins in pancreatic and other periampullary adenocarcinomas." (PMID 32587323, 2020). "Further studies on PODXL in esophageal and gastric adenocarcinoma are warranted to validate its role as a prognostic biomarker and to explore whether it also may be useful as a treatment response predictive biomarker, as suggested in previous studies on colorectal and periampullary cancer." (PMID 27478410, 2016).
urothelial bladder cancer (5 papers, 2014 to 2020). "In PDAC, the proportion of tumors with high cytoplasmic or membranous PODXL expression was relatively large (21.8% and 44.0%, respectively) compared to corresponding percentages in studies of colorectal, breast, or urothelial bladder cancer." (PMID 26053486, 2015). "Furthermore, membranous PODXL expression has been suggested to correlate with poor prognosis in colorectal and urothelial bladder cancers." (PMID 26053486, 2015). "In light of the apparently contrasting prognostic value and intercorrelation of ezrin and PODXL expression in urothelial bladder cancer, it will be of interest to investigate the existence of a negative functional cooperativity between these proteins in this cancer form." (PMID 24885195, 2014).
acute lymphoblastic leukemia (4 papers, 2017 to 2024). Leukemia with an acute onset, characterized by the presence of lymphoblasts in the bone marrow and the peripheral blood. "This study explored the impact of predicted miRNAs on DNA methyltransferases (DNMTs) and the PODXL gene in Nalm6 cells, revealing the significance of these miRNAs in acute lymphocytic leukemia (ALL)." (PMID 38879474, 2024).
gastric adenocarcinoma (4 papers, 2015 to 2020). "In summary, we have shown that PODXL is commonly expressed in esophageal and gastric adenocarcinoma and associated with lymph node metastases and high grade tumors." (PMID 27478410, 2016). "In esophageal and gastric adenocarcinoma, PODXL expression is an independent prognostic biomarker for reduced time to recurrence and poor overall survival." (PMID 27478410, 2016). "In this study on resected esophageal and gastric adenocarcinoma we have shown that PODXL is expressed in the majority of cases and correlates with poor survival, but in the subgroup of patients with PODXL negative cancers the prognosis was excellent." (PMID 27478410, 2016). "The aim of this study was to investigate the impact of PODXL expression on survival in esophageal and gastric adenocarcinoma." (PMID 27478410, 2016). "By tumor-tissue microarrays and immunohistochemistry we evaluated PODXL expression in tumor specimens from 337 patients who underwent surgery for gastric adenocarcinoma at Helsinki University Hospital." (PMID 26674770, 2015). "In esophageal and gastric adenocarcinoma combined, the prognostic significance of PODXL expression on TTR was confirmed in unadjusted Cox regression analysis (HR = 5.36, 95 % CI 1.68-17.06, p = 0.005) and remained significant in the adjusted model (HR = 3.39, 95 % CI 1.01-11.35, p = 0.048)." (PMID 27478410, 2016). "In osteosarcoma cell lines, PODXL has been shown to promote chemoresistance to cisplatin, which is particularly interesting since platinum compounds (cisplatin and oxaliplatin) are important cytotoxic drugs in the treatment of esophageal and gastric adenocarcinoma." (PMID 27478410, 2016).
hepatocellular carcinoma (4 papers, 2013 to 2025). A malignant tumor that arises from hepatocytes. "Studies show that the interactions of PODXL with ezrin and CLIC5 are associated with invasiveness and migration of Huh7 hepatocellular carcinoma (HCC) cell lines." (PMID 34201212, 2021). "The majority of studies on PODXL have focused on its role in hepatocellular carcinoma (HCC)." (PMID 41462970, 2025). "In this study, we examined the expression of EZR, CLIC5 and PODXL at the mRNA and protein levels in a modified hepatocyte resistant model (MHRM) and in cases of human hepatocellular carcinoma (HCC)." (PMID 26135398, 2015).
Wilms tumor (4 papers, 2013 to 2023). An embryonal neoplasm characterized by the presence of epithelial, mesenchymal, and blastema components. "Expression of MAFB and PODXL has been reported in Wilms tumor cell lines and expression of PODXL has been observed in prior microarray analyses of Wilms tumors of varying histology." (PMID 37815464, 2023). "Nevertheless, to our knowledge, our findings provide the first evidence of the podocyte lineage markers MAFB and PODXL at protein level in Wilms tumor." (PMID 37815464, 2023). "We were interested to study the effect of Canagliflozin on podocyte health by quantifying the exosome expression for Nephrin, Wilm’s Tumor (WT-1) and podocalaxyn like protein 1 (PODXL) in urine samples from placebo and Canagliflozin group." (PMID 33581737, 2021). "We were interested to study urinary exosomal expression for nephrin, renal Wilm’s Tumor (WT-1) and podocalyxin like protein 1(PODXL) in urine samples from placebo and linagliptin group." (PMID 32493344, 2020).
cyst (3 papers, 2016 to 2024). A sac-like closed membranous structure that may be empty or contain fluid or amorphous material. "Our study reveals that PODXL plays a pivotal and broader role in cyst development than previously expected." (PMID 27040773, 2016). "The same cyst-to-cyst variability is observed in Rab35-depleted cysts, until internalized PODXL is fused back to the ECM-facing membrane." (PMID 27040773, 2016). "Altogether, these results indicate that PODXL is a genuine Rab35-interacting protein and suggest that Rab35 could play a critical role in early steps of cyst development." (PMID 27040773, 2016). "To test whether the interaction between PODXL and Rab35 was essential for normal cyst polarity, we designed a C-terminal mutant of PODXL unable to bind Rab35." (PMID 27040773, 2016). "Thus, a PODXL mutant unable to interact with Rab35 triggers inversion of cyst polarity from the two-cell stage by preventing fusion of PODXL vesicles at the first cell–cell interface, exactly as observed after Rab35 depletion." (PMID 27040773, 2016). "At later stages, IRSp53 and PODXL were concentrated at the AMIS, and when the cyst was formed, IRSp53 and PODXL co-stained along the lumen." (PMID 32665580, 2020). "During the initial phases of cyst development, IRSp53 and RAB35 were enriched along the opposing cell–cell membrane prior to the arrival of PODXL." (PMID 32665580, 2020). "(A,B) Human pluripotent stem cells (hPSC)-derived pluripotent cyst (hPSC-pluripotent cyst, Glass-3D in A) and amnion cyst (Glass-3D+BMP in B) assays: immunofluorescence (IF) images show hPSC-pluripotent (A) and -amnion (B) cysts stained for PODXL (lumen, magenta) and DNA (nuclear shape, blue)." (PMID 39051990, 2024). "As a consequence, expression of Rab35Q67L-Mito resulted in the appearance of disorganized cysts without lumen, since PODXL-positive vesicles were tethered around mitochondria throughout cyst development (48-h cysts)." (PMID 27040773, 2016). "Importantly, replacing endogenous PODXL with GFP-PODXL V496A/Y500A was sufficient to invert cyst polarity, without the need to deplete Rab35 (arrow)." (PMID 27040773, 2016).